MMP9 (matrix metallopeptidase 9)
Diseases named in the same sentence as MMP9 in open-access papers (continued):
Sharing a sentence is not in itself a finding about the gene and the disease.
metastatic tumors (39 papers, 2005 to 2025). "Some miRNAs, including miR-340, can induce the migration of these cells in human BC cell lines by regulating the expression of MMP-2 and MMP-9; however, silencing of miR-340 expression is associated with high-grade and metastatic tumors." (PMID 41356146, 2025). "The enzymes elastase, cathepsin G, and MMP9 secreted by neutrophils have been associated with progression in metastatic disease." (PMID 39596977, 2024). "In particular, MMP2 (gelatinase-A) and MMP9 (gelatinase-B) are deeply associated with the presence of metastatic tumors." (PMID 36612089, 2022). "The secretion of MMP-2 and MMP-9 by cancer cells is an important mechanism of the cell invasion process since these enzymes degrade basal membrane components such as type IV collagen, a process associated with highly invasive and metastatic tumors." (PMID 38137922, 2023). "In the metastatic tumors, our study predominantly found a significant increase in macrophages expressing CCL2, MGP, SPP1, and MMP9, which have been previously associated with tumor cell invasion, metastasis, and immunoresistance." (PMID 40858590, 2025). "There are generally high MMP-9 mRNA or protein levels in thyroid tumor tissues, malignant tumor tissues, metastatic tumor tissues, and other samples with a high degree of malignancy rather than a low degree." (PMID 37175113, 2023). "As a result of CASP-1 activation, matrix metalloproteinase 9 (MMP-9) is produced, which plays a role in the progression of radioresistant BC to metastatic disease." (PMID 37300757, 2023). "Neutrophil extracellular traps release neutrophil elastase and MMP-9, which induce the proliferation of latent metastatic cancer cells and lead to metastatic tumor formation." (PMID 35701829, 2022). "In HNSCC patients, significantly higher MMP-3, MMP-9 and vimentin levels were found in metastatic tumors." (PMID 28489600, 2017). "Levels of MMP9 mRNA and mature protein have both been shown to be elevated in malignant prostatic tissue, particularly in aggressive and metastatic tumours." (PMID 21266977, 2011). "High levels of MMP-3, MMP-9 and VEGF have all been associated with metastasis in NPC and can therefore serve as endpoint measurement for metastatic disease." (PMID 20964870, 2010). "These tumor cells showed the expression of Ki-67 (90%), VEGF (score 4), COX-2 (score 4) and MMP-9 (score 4) that are known to be expressed in invasive and metastatic tumors." (PMID 21044318, 2010). "The expression of MMP-9 correlated with an aggressive, advanced invasive or metastatic tumor phenotype." (PMID 19624845, 2009). "However, a discernible trend was observed, suggesting that, in comparison to primary tumours, SRC‐1 and MMP‐9 expression tends to be increased in metastatic tumours." (PMID 38506084, 2024). "Similarly, MMP9 inhibition reduced tumor angiogenesis and significantly reduced the growth of metastatic tumors." (PMID 36560848, 2023). "The expression of p-STAT3, STAT3, MMP-2, and MMP-9 in metastatic tumors by western blot analysis." (PMID 34526411, 2021). "Furthermore the down-regulation of E-cadherin and increased activity of matrix metalloproteinase 9 (MMP9) has been reported in metastatic tumors." (PMID 28404939, 2017). "Of the known MMPs studied in the prostate, MMP9 overexpression correlates with metastatic disease." (PMID 21266977, 2011). "The differential expression of MMP3 in primary and metastatic tumours of patient 1 and 7 and of MMP9 in patient 1 and 15 could be confirmed by quantitative real-time PCR." (PMID 16189523, 2005). "In metastatic tumors, our study identified a significant presence of macrophages expressing CCL2, MGP, SPP1, and MMP9, which are associated with various aspects of tumor metastasis and may play a crucial role in preparing the metastatic niche for malignant cell growth." (PMID 40858590, 2025). "Another study indicated that inhibition of MMP-2/MMP-9 improves the efficacy of PD-1 or CTLA4 blockade in the treatment of primary and metastatic tumors." (PMID 35178444, 2022).
metastatic tumors (continued). "It has been confirmed that the expression levels of MMP-9 and MMP-2 in GC, especially in metastatic tumors, are noticeably higher than those in normal gastric mucosa." (PMID 34540679, 2021). "MMP-9 and MMP-2, which are highly expressed in metastatic tumors, are the only two type IV collagenases that are necessary prerequisites for cell invasion." (PMID 28878295, 2017). "The highest signal was from MMP-3 like it does in the metastatic tumors (mean IOD 28,600), followed by MMP-1 (mean IOD 20,200), MMP-9 (mean IOD 13,200), and TIMP-1 (mean IOD 12,300)." (PMID 27975070, 2016). "MMP-9 and VEGF are expressed during invasive OSCCs of the tongue and in metastatic tumors that tend to express higher levels of VEGF and MMP-9, than nonmetastatic tumors." (PMID 23365550, 2013). "Our results show that the expression of MMP9 in all stroma cell types does not differ between non-metastatic and metastatic disease." (PMID 33920263, 2021). "The aim of this study was to, for the first time, compare in OSCC the frequency of AR, VEGF, MMP9, HiF1beta and Ki67 between the non-metastatic and metastatic disease." (PMID 33920263, 2021). "Frequency of HiF 1beta and MMP9 positive cells significantly differed between non-metastatic and metastatic disease in epithelium only and AR positive cells significantly differed between non-metastatic and metastatic disease in stroma only." (PMID 33920263, 2021). "MMP7, MMP13, and MMP10 were upregulated, and MMP12 and MMP9 were downregulated in metastatic tumours compared with nonmetastatic tumours." (PMID 31996191, 2020). "Also in metastatic diseases, there is a significantly increased frequency of VEGF positive lymphocytes related to a cytoplasmic AR ≥ 20% and the frequency of MMP9 positive macrophages was significantly increased regardless of the percentage of AR positive neoplastic epithelial cells." (PMID 33920263, 2021). "However, when the expression was analyzed in stromal macrophages and lymphocytes separately, a significant difference of expression of MMP-9 between non-metastatic and metastatic disease was found for macrophages." (PMID 33920263, 2021). "Thus, the aim of this study was to compare the frequency of AR, HIF-1 beta, VEGF, Ki67 and MMP9 levels between non-metastatic and metastatic disease in the stroma and epithelium of OSCC." (PMID 33920263, 2021). "Thus, although MR was shown to be positive for VEGF lymphocytes and MMP9 macrophages between non-metastatic and metastatic disease, it was clear that the increase was most pronounced for TNM3." (PMID 33920263, 2021). "Therefore, VEGF is a candidate to be blocked and controlled and to prevent the activation of the androgen receptor (AR)/phosphatidylinositol 4-phosphate 5-kinase type-1 alpha (PIP5K1α)/AKT/MMP-9/VEGF signaling axis required for cell survival and invasion of metastatic tumors." (PMID 31921634, 2019). "Instead, a tendency to diminish the expression of MMP-9 in no metastatic tumors (N0) was observed." (PMID 27975070, 2016). "Our study has for the first time shown a difference in AR, VEGF, MMP9, HiF 1beta and Ki67 positive cell levels in the stroma and neoplastic epithelium of OSCC between non-metastatic and metastatic disease." (PMID 33920263, 2021). "Based on the negative impact of anti‐MMP9 antibody in the pre‐clinical PDAC models in terms of tumour stroma, metastasis and EMT, our data support the possible advantages of anti‐MMP9 antibody therapy in PDAC patients with localized non‐metastatic disease." (PMID 30941918, 2019). "Evaluation of expression of MMP-1, MMP-3, MMP-9, and TIMP-1 in 54 samples from patients with no metastatic tumors in lymph nodes was indirectly estimated by obtaining numeric values of intensity IOD, from the corresponding immunohistochemistry results (standard process)." (PMID 27975070, 2016).
osteoporosis (39 papers, 2012 to 2025). A condition of reduced bone mass, with decreased cortical thickness and a decrease in the number and size of the trabeculae of cancellous bone (but normal chemical composition), resulting in increased fracture incidence. "Paradoxically, glucocorticoids used to suppress chronic inflammation paradoxically increase osteoporosis risk, while tetracycline inhibits MMP-9 activity to ameliorate bone loss, highlighting the complex interplay between inflammation and osteoclastogenesis." (PMID 40244002, 2025). "Excessive MMP-9 activity is associated with the development of many skeletal diseases such as bone cancer, spinal degeneration and osteoporosis." (PMID 39407715, 2024). "Far to our knowledge, we are the first to study the correlation between serum dyslipidaemia and MMP-9 gene expression in bones as a probable molecular connection between osteoporosis and cardiovascular diseases risk factors." (PMID 34610044, 2021). "The mechanisms of inhibition were via suppression of osteoporosis-related protein expression (NFATc1 and c-Fos), gene expression (Nfatc1, Ca2, Acp5, mmp9, CtsK, Oscar, and Atp6v0d2), and inhibited bone loss induced in the OVX model." (PMID 33859705, 2021). "Since MMP-9 is a key regulator of osteoclast formation, and is heavily implicated in osteoporosis, it is reasonable to develop anti-osteoporosis drugs targeting MMP-9." (PMID 31430857, 2019). "ICT significantly inhibited OC differentiation and the expression of related genes (Trap, Mmp9, and Nfatc1), reduced bone loss, and improved osteoporosis and bone trabecular structure, and inhibited the levels of TRAP and RANKL in the serum and increase the level of osteoprotegerin (OPG)." (PMID 41019997, 2025). "And it was reported that the development of osteoporosis was also associated with the degradation of extracellular matrix caused by the MMP9 that could be secreted from OCs." (PMID 37464262, 2023). "Together, these findings indicate that dual targeting of Mmp9 and Ctsk may be useful for blocking osteoporosis induced bone loss." (PMID 36147479, 2022). "Taken together, as compared to RANKL/OPG, MMP-9 could be considered a simpler and more sensitive marker for osteoporosis and potentially for increased cardiovascular diseases risk as will be discussed further." (PMID 34610044, 2021). "In any event, the bone defect caused by atp6v1h deficiency through activation of mmp9/13 represents a novel finding that offers potential therapeutic entry points for related diseases, since MMP9 levels have been correlated to severity of osteoporosis." (PMID 28158191, 2017). "Therefore, extending MMP-9’s effect to migration may then contribute to osteoclast recruitment and in vivo bone loss (anti-osteoporosis effect)." (PMID 30501117, 2018). "MMP9 is closely related to osteoporosis or osteoclasts, and MMP9 is also one of the important targets for our network pharmacological prediction." (PMID 40089686, 2025). "In this study, the downregulation of IL-6, TNF-α, IL-1β, MMP3, MMP9, and caspase-3 by curculigoside aligns with previous findings that these factors mediate osteoblast injury and extracellular matrix degradation in osteoporosis." (PMID 40917365, 2025). "MMP-9 acts as a dual regulator of osteoclastogenesis and inflammation, suggesting therapeutic potential for osteoporosis management." (PMID 40244002, 2025). "The enzyme analysis results of all these studies revealed that MMP2, MMP9, TIMP1, and TIMP2 were low and cathepsin K was high in MPS III patients, and that the patients had low bone density and increased osteoporosis risk." (PMID 40104299, 2025). "Our findings establish MMP-9 as a therapeutic target with dual action in balancing bone resorption and inflammation, representing a paradigm shift in osteoporosis management." (PMID 40244002, 2025).
osteoporosis (continued). "Clinical observations revealed elevated circulating MMP-9 levels in patients, particularly those with osteoporosis, suggesting MMP-9 as a potential biomarker for increased bone resorption." (PMID 39947684, 2025). "Downregulation of Bglap, upregulation of Rankl and Trap, and a tendency toward Mmp9 and Tsc2 upregulation clearly proved osteoporosis development in Dex-treated animals." (PMID 41373561, 2025). "MMP-9 in the osteoporosis microenvironment is mainly involved in the degradation of collagen and proteoglycans." (PMID 38355572, 2024). "Dihydroquercetin can inhibit RANKL-induced osteoclast differentiation and gene expression, including TRAP and MMP-9, showing potential for treating osteoporosis, bone resorption, and related diseases such as RA." (PMID 38999143, 2024). "In turn, the MMP-9 gene was singled out during gene clustering analysis as one of the secondary genes in terms of involvement in osteoporosis." (PMID 38138968, 2023). "A previous study illustrated that MMP9 exerted a crucial role in pathogenesis of osteoporosis, and the inhibitory effect on bone resorption was emerged by inhibiting the expression of MMP9." (PMID 37089711, 2023). "This information suggests that NFATC1, cSRC, MMP-9 and Cathepsin K were the four core indicators of osteoclastogenesis involved in osteoporosis." (PMID 36431913, 2022). "This study presents matrix metalloproteinase-9 (MMP-9), as a simple molecular link more consistently associated with the pathophysiology of both osteoporosis and CVD risk factors." (PMID 34610044, 2021). "MMP-9, is essential for initiating the osteoclastic resorption process in cases of osteoporosis by removing the collagenous layer from the bone surface before demineralization can start." (PMID 34610044, 2021). "The association between MMP-1, MMP-2, MMP-3, MMP-9, and MMP-13 with the pathogenesis of osteoporosis has been demonstrated in different studies." (PMID 32071923, 2020). "Another protease, MMP-9, was found to contribute to osteoporosis, which is characterized by increased osteoclastogenesis and a decreased number of active osteoblasts (for bone formation)." (PMID 33352765, 2020). "While Mmp2-null mice have osteoporosis, Mmp9-null and Mmp13-null mice exhibit enlarged hypertrophic zones and osteopetrosis." (PMID 28158191, 2017). "Increased serum levels of MMP9 are an indicator of decreased bone density and osteoporosis." (PMID 40395806, 2025). "Interestingly, IMB-R38 treatment significantly decreased mRNA levels of Mmp9, Mmp13, Mmp2, and Il-6, which play a vital role in both osteoporosis and inflammation." (PMID 41465573, 2025). "Therefore, down-regulating the expression of osteoclast-related factor MMP9 is helpful to inhibit osteoporosis." (PMID 40089686, 2025). "In a further study, Zhang PF found that serum MMP-9/TIMP-1 ratios in COPD patients with osteoporosis were significantly higher (high MMP-9, low TIMP-1) than in patients with normal bone mineral density (BMD) and that these ratios were negatively correlated with BMD." (PMID 36991363, 2023). "In addition, they examine the ability of MMP-9 in classifying patients with respect to the onset of osteoporosis." (PMID 38138968, 2023). "A significant positive correlation was noticed between MMP9 gene expression and serum TC and TGs as a result of osteoporosis induction (p <0.001, r = 0.877 and p <0.001, r = 0.835 respectively) while HDL showed a negative correlation with MMP_9 gene expression (p <0.001, r = -0.830)." (PMID 34610044, 2021). "This study presents MMP-9, a downstream molecule executing the destructive aspect of RANKL/OPG system, as a simple molecular link more consistently associated with the pathophysiology of both osteoporosis and CVD risk factors." (PMID 34610044, 2021).
osteoporosis (continued). "To conclude, Alendronate reduced significantly MMP-9, improved significantly CVD risk factors and efficiently treated osteoporosis as evident by histological examination and BTM levels in Alendronate-treated group as compared to the untreated osteoporotic rats and the control sham-operated rats." (PMID 34610044, 2021). "Since MMP-9 was demonstrated to regulate the occurrence and development of osteoporosis it may serve as a potential marker for the prediction and diagnostic method for postmenopausal osteoporosis." (PMID 32071923, 2020). "Finally, human studies confirmed the overexpression of MMP-9 in subjects suffering from osteoporosis." (PMID 32071923, 2020). "In accordance with the current knowledge about the role of MMP-9 in bone remodeling and osteoporosis, we assumed that the serum level of MMP-9 could serve as an important marker for early assessment of treatment response." (PMID 32071923, 2020). "Therefore, MMP2 and MMP9 are expected to increase in osteoporosis activities." (PMID 40104299, 2025). "Curculigoside is likely to treat osteoporosis through targets such as MMP3, MMP9, IL-6, and caspase-3, acting on signaling pathways including Rap1 and TNF." (PMID 40917365, 2025). "MMP-9 has been shown to be an integral part of many diseases where modulation of the ECM is a key step such as cancer, osteoporosis and fibrosis." (PMID 26219353, 2015). "Third, CD9/CD81 DKO macrophages are spontaneously activated and produce more MMP-9 than WT macrophages, and CD9/CD81 DKO mice suffer from age-related pulmonary emphysema and osteoporosis, phenotypes akin to human COPD." (PMID 24040034, 2013). "In COPD patients with osteoporosis, circulating MMP-9 levels were increased, whereas TIMP-1 and -2 were not different and associated with bone loss (reduced bone mass and osteoporosis)." (PMID 36991363, 2023). "The serum MMP-9 concentration was observed to be negatively correlated with BMD (bone mineral density) and is considered as a biochemical marker of bone resorption and remodeling and an important marker in the early diagnosis of osteoporosis." (PMID 32071923, 2020). "Our findings demonstrate that the tetracycline analogs suppress osteoclastogenesis via MMP-9-mediated H3 tail cleavage, and suggest that MMP-9 inhibition could offer a new strategy for the treatment of glucocorticoid-induced osteoporosis." (PMID 31430857, 2019). "Circulating serum MMP-9 showed a trend of increasing levels from patients with a normal BMD, through patients with a reduced BMD, to patients with established osteoporosis." (PMID 38138968, 2023). "Although measurements of circulating MMP-9 and TIMP-1 allowed us to detect effects of exercise, as of today, they have no real role in the diagnosis of osteoporosis and/or follow-up of osteoporotic patient's response to treatment." (PMID 32071923, 2020).